GOLGA6L25 (golgin A6 family like 25)
Synonyms: GOLGA6L25P
Tractability: No criterion of Open Targets' tractability assessment is met for any kind of drug.
Gene: Protein-coding gene on chromosome 15 (28,553,568 to 28,563,779, forward strand). Ensembl gene ENSG00000227717.
Genetic constraint (gnomAD): Loss-of-function variants: 0 observed, 1.68 expected, observed/expected ratio (o/e) 0, 90% interval 0 to 1.48. That is too few expected variants to judge how well the gene tolerates losing a copy. Missense variants: 2 observed, 20.96 expected, observed/expected ratio (o/e) 0.0954, 90% interval 0.038 to 0.3. Synonymous variants: 0 observed, 4.67 expected, observed/expected ratio (o/e) 0, 90% interval 0 to 0.64.
Homologues: Paralogues in human: GOLGA6L24 (99% identical), GOLGA6L22 (98% identical), GOLGA6L6 (81% identical), GOLGA6L26 (73% identical), GOLGA6L1 (73% identical), GOLGA6L2 (39% identical), GOLGA6L7 (36% identical), GOLGA6L4 (17% identical), GOLGA6L10 (16% identical), GOLGA6L9 (16% identical).